AZGP1 (alpha-2-glycoprotein 1, zinc-binding)
Description:
Stimulates lipid degradation in adipocytes and causes the extensive fat losses associated with some advanced cancers. May bind polyunsaturated fatty acids.
Synonyms: ZAG; ZA2G
Tractability: Small molecule: a structure with a bound ligand is known; it has a binding pocket of medium quality. Antibody: its Gene Ontology location is reachable by antibodies, with high confidence; UniProt places it where antibodies can reach, with medium confidence; UniProt predicts a signal peptide or a membrane-spanning region.
Gene: Protein-coding gene on chromosome 7 (99,966,720 to 99,976,066, reverse strand). Ensembl gene ENSG00000160862.
Subcellular location: Secreted
Subcellular location (Human Protein Atlas): Vesicles; Nucleoplasm; Predicted to be secreted
Pathways (Reactome):
Transport of small molecules: Miscellaneous transport and binding events
Gene Ontology:
Molecular function: protein binding; protein transmembrane transporter activity; RNA nuclease activity
Biological process: cell adhesion; detection of chemical stimulus involved in sensory perception of bitter taste; antigen processing and presentation of endogenous peptide antigen via MHC class I via ER pathway, TAP-independent; antigen processing and presentation of endogenous peptide antigen via MHC class Ib; immune response; negative regulation of cell population proliferation; positive regulation of T cell mediated cytotoxicity; protein transmembrane transport
Cellular component: extracellular exosome; extracellular region; nucleus; external side of plasma membrane
Genetic constraint (gnomAD): Loss-of-function variants: 29 observed, 34.65 expected, observed/expected ratio (o/e) 0.84, 90% interval 0.62 to 1.14. The upper end of that interval is the gene's LOEUF score, 1.14, which puts it in group 5 of 6, group 1 being the genes least tolerant of losing a copy. Missense variants: 361 observed, 385.18 expected, observed/expected ratio (o/e) 0.94, 90% interval 0.86 to 1.02. Synonymous variants: 135 observed, 150.25 expected, observed/expected ratio (o/e) 0.9, 90% interval 0.78 to 1.04.
Homologues: Orthologues: chimpanzee AZGP1 (99% identical), macaque AZGP1 (92% identical), guinea pig AZGP1 (66% identical), rabbit AZGP1 (65% identical), dog AZGP1 (61% identical), rat Azgp1 (60% identical), mouse Azgp1 (59% identical), zebrafish mhc1uba (25% identical), zebrafish mhc1uka (24% identical), zebrafish mhc1uma (22% identical). Paralogues in human: HLA-B (36% identical), HLA-A (35% identical), HLA-C (34% identical), HLA-F (34% identical), HLA-G (34% identical), MR1 (33% identical), HFE (33% identical), HLA-E (32% identical), FCGRT (28% identical), MICA (24% identical), MICB (24% identical), CD1A (23% identical), and 10 more.
Diseases named in the same sentence as AZGP1 in open-access papers:
AZGP1 is named in the same sentence as 141 diseases in open-access papers, as found by Europe PMC text mining. Sharing a sentence is not in itself a finding about the gene and the disease. The quoted sentences say what the papers report.
Obesity (48 papers, 2010 to 2025). Accumulation of substantial excess body fat. "Conversely, the deletion of Azgp1 in POMC neurons increased susceptibility to obesity and aggravated metabolic dysfunction." (PMID 38643150, 2024). "This previously undiscovered role of AZGP1 in the hypothalamus indicates that it is a potential drug target for the treatment of obesity and its associated metabolic disorders." (PMID 38643150, 2024). "The change of AZGP1 level is closely associated with obesity and related complications, such as diabetes, obesity and polycystic ovary syndrome." (PMID 37583433, 2023). "In the epidemic of obesity, AZGP1 is implicated in polygenic traits and age-dependent alterations in the genetic regulation of obesity." (PMID 35677823, 2022). "AZGP1 appears as a marker of sexual dimorphism, obesity and metabolic syndrome encodes an adipokine with putative antidiabetic properties." (PMID 23028366, 2012). "Together, these observations and the current findings related to AZGP1 indicate that increasing leptin sensitivity could be a potential therapeutic strategy to combat obesity-associated metabolic disorders." (PMID 38643150, 2024). "Conversely, mice with inducible deletion of Azgp1 in POMC neurons exhibit the opposite metabolic phenotypes, showing increased susceptibility to diet-induced obesity." (PMID 38643150, 2024). "While high expression of AZGP1 in Western diet mice agrees with its known functions in lipid degradation processes and impaired insulin sensitivity in obesity, AZGP1 was also suggested to be involved in bitter taste perception by Gene Ontology analyses." (PMID 34066295, 2021). "It was suggested that AZGP1 is part of a mechanism by which growth hormone (GH) modulates subcutaneous adipose tissue lipid metabolism indicating a potential role for GH-AZGP1 axis in protecting against the development of obesity." (PMID 33578947, 2021). "The overexpression of AZGP1 in the MBH improved glucose/lipid metabolism and prevented the development of obesity." (PMID 38643150, 2024). "The AZGP1 gene is involved in the TNF-alpha and IL-1 beta (IL-1b) pathways, which are involved with the occurrence of dyslipidemia and inflammation in adipocytes, leading to the development of obesity and type 2 diabetes diseases." (PMID 35804531, 2022).
prostate carcinoma (32 papers, 2012 to 2026). A carcinoma that arises from epithelial cells of the prostate gland. "A tissue microarray containing 11,152 prostate cancers showed that the reduced AZGP1 expression was associated with adverse prostate cancer prognosis through the regulation of PTEN." (PMID 38874510, 2024). "Loss of AZGP1 expression is a biomarker associated with progression to castration resistance, development of metastasis, and poor disease-specific survival in prostate cancer." (PMID 38659028, 2024). "AZGP1 is a negative regulator of angiogenesis, such that loss of AZGP1 promotes angiogenesis in prostate cancer." (PMID 38659028, 2024). "A multicenter study focusing on the association between the expression level of AZGP1 and the prognosis of patients with prostate cancer showed that decreased expression of AZGP1 was related to poor prognosis and recurrence of prostate cancer." (PMID 35433689, 2022). "In prostate cancer, the loss of AZGP1 is associated with worse clinical outcomes and a risk of recurrence, independently forecasts biochemical relapse 13-15." (PMID 31632499, 2019). "In addition, a clinical study included 191 patients who underwent androgen deprivation therapy showed that low AZGP1 expression was associated with a shorter survival time in prostate cancer patients." (PMID 38874510, 2024). "HMGN3 is a regulator of a plethora of genes, some of which are involved in glucose and fat metabolism, including the putative tumor suppressor gene AZGP1, inactivation of which has been linked to tumor progression, poor prognosis, and increased cell proliferation in prostate cancer before." (PMID 29312579, 2017). "In prostate cancer, AZGP1 also showed significant diagnostic value as a serum marker." (PMID 25561225, 2014). "However, an inverse association between AZGP1 expression with tumor stage was found in prostate cancer." (PMID 22625427, 2012). "Factor 10 displays the highest signal in normal glands, with high expression of MSMB and AZGP1, which are reported to be significantly downregulated in prostate cancer." (PMID 40167331, 2025). "A similar result was obtained from a Chip-Seq study that AZGP1 acted as an androgen-responsive gene to mediate proliferation and metastasis of prostate cancer cell via the contribution of androgen receptor." (PMID 38874510, 2024). "The effects of AZGP1 under- or over-expression in prostate cancer cells were evaluated by in vitro cell proliferation, migration, and invasion assays." (PMID 38659028, 2024). "In our analysis, we also predicted the formononetin’s targets such as INSR and AZGP1 to control the metabolisms in the tissue cell of prostate cancer." (PMID 38874510, 2024). "This study sheds light on the anti-angiogenic characteristics of AZGP1 in the prostate and provides a rationale to target AZGP1 to inhibit prostate cancer progression." (PMID 38659028, 2024). "AZGP1 expression and microvessel density were measured in human prostate cancer samples on a tissue microarray of 215 independent patient samples." (PMID 38659028, 2024). "Instead, these tumors displayed decreased microvessel density compared to xenografts derived from PC3 and DU145 control cells, suggesting that AZGP1 functions to inhibit angiogenesis in prostate cancer." (PMID 38659028, 2024). "Loss or attenuation of AZGP1 expression has been shown to be associated with reduced RFS and metastatic survival in prostate cancer patients." (PMID 37669935, 2023). "Studies showed that AZGP1 participated in the regulation of tumorigenesis, such as breast cancer, prostate cancer, liver cancer, gastric cancer, colon cancer and LUAD." (PMID 35433689, 2022). "In lung adenocarcinoma and prostate cancer, patients with high levels of AZGP1 had better survival than those with low levels of AZGP1." (PMID 22625427, 2012).
prostate carcinoma (continued). "Looking specifically at AR-associated gene expression in our treatment-naïve primary prostate cancer samples, our AIPC cohort demonstrates significantly lower expression of AR, FOXA1, TMPRSS2, KLK3, AZGP1, and several other AR-associated genes when compared with the non-AIPC cohort." (PMID 39859392, 2025). "However, high expression of AZGP1 cells in prostate cancer has been reported to increase proliferation and invasion." (PMID 38659028, 2024). "In vivo xenografts generated from AZGP1 under- or over-expressing prostate cancer cells were used to determine the role of AZGP1 in prostate cancer tumor growth, and subsequent proteomics analysis was conducted to elucidate the mechanisms of AZGP1 action in prostate cancer progression." (PMID 38659028, 2024). "Additionally, tumor microarray analysis shows that AZGP1 expression is negatively correlated with blood vessel density in human prostate cancer tissues." (PMID 38659028, 2024). "The exact role of AZGP1 in prostate cancer progression remains elusive." (PMID 38659028, 2024). "AZGP1 knockout and overexpressing prostate cancer cells were generated using a lentiviral system." (PMID 38659028, 2024). "Furthermore, the inverse correlation of AZGP1 expression and microvessel density observed in localized human prostate cancers confirms the inhibitory effect observed in the animal models." (PMID 38659028, 2024). "Similarly, AZGP1, as with other kinds of secreted proteins, was also verified to be involved in the process of the proliferation and metastasis of prostate cancer cells induced by the AR." (PMID 39771106, 2024). "Notably, AZGP1 was initially identified as a potential biomarker of prostate cancer, and its expression was subsequently shown to be closely associated with the histologic grade of breast cancer." (PMID 38245780, 2024). "Recent studies have revealed that AZGP1 could suppress the malignant phenotype in several cancers, including GC, colorectal cancer, prostate cancer, hepatocellular carcinoma, and so on." (PMID 36831602, 2023). "Abundant evidence demonstrates that the loss of expression of AZGP1—just like Zn—in tumor cells is a negative prognostic biomarker for different solid tumors, including breast, gastric, esophageal, soft tissue and prostate cancers." (PMID 31740720, 2019). "AZGP1 was found to be a potential biomarker for prostate cancer and could be used for early diagnosis." (PMID 25561225, 2014). "Absent or weak AZGP1 expression is reported to be associated with shorter recurrence-free and metastasis-free survival of prostate cancer patients." (PMID 22625427, 2012). "In prostate cancer, AZGP1 could be served as a potential serum maker, being expressed in malignant prostatic epithelium." (PMID 22625427, 2012). "Reports demonstrated that poorly differentiated tumors expressed less AZGP1 than well differentiated tumors in most of popular human tumors, such as breast cancer, prostate cancer, oral squamous cell carcinomas, epidermal tumors, sweat gland tumors, pancreatic cancer and cervical cancer." (PMID 22625427, 2012). "To evaluate whether AZGP1 could affect microvessel density in AR + clinically localized human prostate cancer, we used the CellDIVE platform to perform multiplex immunohistochemistry analyses on a human prostate cancer tissue microarray (TMA) containing 215 cases." (PMID 38659028, 2024). "The analysis of AZGP1 expression in malignant prostate epithelium in prostatectomy specimens from 228 prostate cancer patients revealed that absent or weak AZGP1 expression was associated with clinical recurrence, including localized recurrence, metastasis, or death." (PMID 31632499, 2019).
prostate carcinoma (continued). "Similarly, absent or weak expression of AZGP1 was found to be associated with recurrence and metastasis of prostate cancer patients." (PMID 29357838, 2018). "Moreover, many studies suggest that AZGP1 is a potential serum marker of prostate cancer." (PMID 23935945, 2013). "Six target genes were subjected to protein validation: GPR116, NPY and PLA2G7, three genes over-expressed in ERG+ tissues, and AZGP1, HPGD and TFF3, three genes down-regulated in ERG+ prostate cancer tissues." (PMID 23390522, 2013). "Neither the knockout nor overexpression of AZGP1 exhibited significant effects on prostate cancer cell proliferation, clonal growth, migration, or invasion in vitro." (PMID 38659028, 2024). "Previously, AZGP1 has been reported to possess tumor suppressive properties in breast cancer, prostate cancer, pancreatic cancer and some other malignant tumors; however the role of AZGP1 in primary gastric cancer has not yet been evaluated." (PMID 23935945, 2013).
Insulin resistance (25 papers, 2012 to 2025). Increased resistance towards insulin, that is, diminished effectiveness of insulin in reducing blood glucose levels. "AZGP1 is a lipid mobilizing factor with putative role in insulin resistance as mRNA and protein were low in AT of type 2 diabetes patients and circulating AZGP1 protein inversely correlated with BMI and waist-to-hip ratio." (PMID 25590576, 2015). "AZGP1 levels in the blood are lower in women with PCOS, and AZGP1 could be a cytokine linked to insulin resistance in PCOS patients." (PMID 35677823, 2022).
breast carcinoma (22 papers, 1990 to 2026). "recently reported that AZGP1 was associated with the immune-suppressive phenotype and reduced infiltration of M1-like TAMs in breast cancer, suggesting its role as a regulator of tumor immune response in breast cancer TME." (PMID 40900789, 2025). "Using the METABRIC dataset, we performed GSEA to screen the biological processes associated with AZGP1 expression in breast cancer tissues." (PMID 38349455, 2024). "Secondly, AZGP1 expression has been found to be associated with poor outcomes in several other cancers, including hepatocellular carcinoma, gastric cancer, and breast cancer." (PMID 32726925, 2020). "The association between AZGP1 and tumorigenesis was initially explored in prostate and breast cancer tissues." (PMID 25561225, 2014). "Meanwhile, the AZGP1 diagnostic value in carcinoma effusion or serum of prostate and breast cancer patients has been reported in some studies." (PMID 25561225, 2014). "In silico analyses using public gene expression datasets and analysis of our in-house FCM datasets demonstrated that AZGP1/ZAG is associated with immunosuppressive phenotype and reduces the infiltration of specific immune cell subsets, particularly Mφ, into breast cancer tissues." (PMID 38349455, 2024). "The diagnostic value of AZGP1 in serum of prostate and breast cancer patients has been reported." (PMID 25561225, 2014). "Previous studies have indicated that AZGP1 possesses zinc-binding properties and its expression is reduced in more aggressive cancer lesions, such as PCa, breast cancer, colon cancer, liver cancer, gastric cancer, and lung cancer." (PMID 41535762, 2026). "The results revealed elevated levels of several breast cancer-related genes, including AZGP1, GATA-3, KRT14, XIST, and ESR1." (PMID 40474021, 2025). "Among them, AZGP1 and CRISP3 are associated with breast cancer invasiveness, while SCGB2A2 and SCGB1D2 serve as common markers for disseminated tumor cells (DTCs)." (PMID 40838787, 2025). "The gene detection results demonstrated elevated levels of breast cancer-related genes, including AZGP1, GATA-3, KRT14, XIST, and ESR1." (PMID 40474021, 2025). "The expression of AZGP1 in breast cancer tissues was negatively correlated with the survival of breast cancer patients." (PMID 40474021, 2025). "We systematically analyzed the relationship between the expression of AZGP1/ZAG and the immunological profiles of breast cancer tissues at both the gene and protein level." (PMID 38349455, 2024). "AZGP1/ZAG was associated with an immunosuppressive phenotype and reduced infiltration of specific immune cell subsets, particularly Mφ, into breast cancer tissues." (PMID 38349455, 2024). "Using the METABRIC and SCAN-B gene expression dataset, we analyzed the correlation between AZGP1 expression and the immune cell composition in breast cancer tissues estimated with the CIBERSORTx." (PMID 38349455, 2024). "AZGP1 was also proposed as predictor for breast cancer due to its elevated expression in cancer and normal epithelial adjacent tissues but not in normal tissue of healthy women." (PMID 22625427, 2012). "AZGP1 has been identified as a potential prognostic marker for early-stage breast cancer and a useful immunohistochemical marker of apocrine cell differentiation in human breast tissue." (PMID 20034393, 2009). "The expression of AZGP1 determines the histologic grade of tumors in breast cancer." (PMID 39804726, 2025). "In addition to the inverse correlation between Mφ and AZGP1/ZAG expression in breast cancer tissues, ZAG expression was associated with decreased CD86-positive cells in Mo/Mφ, thus suggesting that ZAG is involved in Mφ differentiation or its function." (PMID 38349455, 2024). "For instance, in component 18, it has been widely described that PIP binds AZGP1 in breast cancer." (PMID 32525929, 2020).
breast carcinoma (continued). "In addition, AZGP1 expression is correlated positively to leptin receptor and negatively to adiponectin receptor and estrogen receptor in breast cancer tissue." (PMID 22625427, 2012). "In this study, we thus aimed to determine the relationship between the expression of AZGP1/ZAG and the immunological profiles of breast cancer tissues at both the gene and protein level." (PMID 38349455, 2024). "This novel study demonstrated the relationship between the immunological profile of the breast cancer microenvironment and AZGP1/ZAG expression, with results consistent with the findings of previous reports, suggesting the immunosuppressive functions of ZAG in animal models of various diseases." (PMID 38349455, 2024). "KLK3 and AZGP1 expression were not strongly correlated with AR expression in all breast cancer subtypes." (PMID 34736512, 2021). "Previous studies suggested that UBE2C expression was accompanied by that of other biomarkers such as AZGP-1, prolactin-inducible protein, and S100A8 or with pituitary tumor-transforming 1 (PTTG1), Survivin and thymidin kinase 1, which might improve outcome prediction in breast cancer." (PMID 24699941, 2014).